OR9I1 (olfactory receptor family 9 subfamily I member 1)
Description:
Odorant receptor.
Synonyms: OR11-228
Tractability: Antibody: UniProt places it where antibodies can reach, with medium confidence; UniProt predicts a signal peptide or a membrane-spanning region; its Gene Ontology location is reachable by antibodies, with medium confidence.
Gene: Protein-coding gene on chromosome 11 (58,116,742 to 58,125,530, reverse strand). Ensembl gene ENSG00000172377.
Subcellular location: Cell membrane
Pathways (Reactome):
Sensory Perception: Expression and translocation of olfactory receptors
Gene Ontology:
Molecular function: olfactory receptor activity; G protein-coupled receptor activity
Biological process: G protein-coupled receptor signaling pathway; sensory perception of smell; detection of chemical stimulus involved in sensory perception of smell
Cellular component: plasma membrane; membrane
Genetic constraint (gnomAD): Loss-of-function variants: 9 observed, 12.85 expected, observed/expected ratio (o/e) 0.7, 90% interval 0.42 to 1.22. The upper end of that interval is the gene's LOEUF score, 1.22, which puts it in group 5 of 6, group 1 being the genes least tolerant of losing a copy. Missense variants: 415 observed, 387.84 expected, observed/expected ratio (o/e) 1.07, 90% interval 0.99 to 1.16. Synonymous variants: 160 observed, 158.8 expected, observed/expected ratio (o/e) 1.01, 90% interval 0.88 to 1.15.
Homologues: Orthologues: chimpanzee OR9I1 (99% identical), macaque OR9I1 (94% identical), dog OR9I1 (84% identical), pig OR9I1 (84% identical), mouse Or9i1b (82% identical), rabbit OR9I1 (82% identical), mouse Or9i1 (82% identical), rat Or9i1b (82% identical), mouse Or9i14 (79% identical), rat Or9i14 (78% identical), rat Or9i13 (77% identical). Paralogues in human: OR9Q2 (61% identical), OR9Q1 (55% identical), OR5AP2 (54% identical), OR5B12 (54% identical), OR5B21 (53% identical), OR5I1 (52% identical), OR5L1 (52% identical), OR5L2 (51% identical), OR8J2 (51% identical), OR5AS1 (51% identical), OR9G4 (51% identical), OR9H1 (51% identical), and 84 more.